GLI2 (GLI family zinc finger 2)
Diseases named in the same sentence as GLI2 in open-access papers (continued):
Sharing a sentence is not in itself a finding about the gene and the disease.
tumor (continued). "Bulk tumor RNA-seq revealed that Gli2 expression was positively correlated to markers of collagen deposition, extra cellular matrix (ECM) organization, and components of Wnt, Notch, and Transforming Growth Factor Beta signaling." (PMID 37444470, 2023). "Conversely, the suppressed ZNFs in GC such as SPOP can impede GC progression, and in vitro tests suggested that overexpressed SPOP can block the invasion and colony formation of tumor cells by suppressing the Hh/GLI2 signaling pathway." (PMID 37174714, 2023). "Arsenic trioxide (ATO) is another Gli inhibitor with the potential to decrease Gli transcriptional activity by binding to Gli1 and Gli2 and has been reported to delay tumor progression in preclinical studies." (PMID 36517618, 2022). "In OSCC, KRT17 is the downstream expressed gene of the glial-associated oncogene homologue 1 and 2 (GLI-1and GLI-2), Moreover, GLI-1 and GLI-2 can effect tumour growth by regulating KRT17 expression." (PMID 35281081, 2022). "In invasive tumors, Gli2/Gli3 KO fibroblasts exclude immunosuppressive myeloid cells and suppress tumor growth by recruiting natural killer cells." (PMID 35867772, 2022). "Strikingly, co-injection of tumor cells with Gli1/Gli2/Gli3 KO fibroblasts promotes tumor growth to the same degree as parental Gli1 KO fibroblasts and WT control fibroblasts." (PMID 35867772, 2022). "HIF1A and TGF-β2 jointly activate the tumor resistance gene GLI2, enhancing intrinsic tumor resistance to chemotherapeutic drugs." (PMID 35659268, 2022). "To assess which types of macrophages are impacted by the loss of Gli2/Gli3, we evaluated the expression of arginase 1 (ARG1), a marker of immunosuppressive tumor-associated macrophages (TAMs)." (PMID 35867772, 2022). "Transgenic mice overexpressing GLI2 develop multiple BCCs and GLI2 is required to maintain tumor growth." (PMID 35505292, 2022). "Studies have shown that Autoimmune regulator (Aire), a transcriptional regulator, induces KRT17 dependent expression in human and mouse tumour keratinocytes and requires GLI-2 induced skin tumour development in mice." (PMID 35281081, 2022). "To study the role of Gli1/Gli2/Gli3 in tumor growth, we performed tumor implantation experiments with Gli KO pancreatic fibroblasts." (PMID 35867772, 2022). "In contrast, depleting NK cells in tumors co-injected with Gli2/Gli3 KO fibroblasts rescues tumor growth, and the resulting tumors are equivalent in size to tumors co-injected with WT fibroblasts." (PMID 35867772, 2022). "Initially, identified from cellular screening assays in 2007, GANT58 and GANT61 were demonstrated to be selective inhibitors of Hh-driven tumor growth because of their capacity to downregulate the transcriptional activity of Gli1 and Gli2." (PMID 36517618, 2022). "This was the first report that demonstrated a novel PTCH1::GLI2 gene fusion in gastroblastoma, and thus expanded the molecular spectrum of this tumor." (PMID 36147912, 2022). "Given the detrimental effects observed when Gli1, Gli2, and Gli3 are deleted at PanIN stages, we next tested how Gli1/Gli2/Gli3 KO fibroblasts impact invasive tumor growth." (PMID 35867772, 2022). "In contrast, Gli1/Gli2/Gli3 KO fibroblasts recruit MDSCs and exclude NK cells, leading to sustained tumor growth." (PMID 35867772, 2022). "Our recent study further found that ependymoma-specific ZFTA fusion genes directly bind to the GLI2 locus to activate it for tumor progression." (PMID 35573667, 2022). "Using publicly available databases, The Cancer Genome Atlas (TCGA), we compared expression levels of GLI1 and GLI2 in intrahepatic CCC with those in non-tumor liver tissues." (PMID 34948011, 2021).
tumor (continued). "This includes overexpression of HH ligand in tumor and tumor microenvironment (TME), loss of function mutation in PTCH1 and SUFU, GLI2 amplifications, and gain of function mutation in SMO." (PMID 34831357, 2021). "Sufu−/−;Spop + /−;Gli2 + /− animals showed normal cerebellar patterning and a significant reduction in tumor incidence." (PMID 34395437, 2021). "And GANT58 is a Gli2 antagonist that inhibits Gli2 nuclear translocation and PTHrP expression in tumor cells to play a role in hindering the ‘vicious circle’." (PMID 33336610, 2021). "BMP-2 and TGF-β1 expression was observed in the cytoplasm of the tumor cells, whereas Gli2 and pSmad2/3 expression was observed in the nucleus of the tumor cells." (PMID 33388078, 2021). "This increased bone destruction causes the release of matrix-derived proteins such as transformation growth factor β (TGF-β), which then feeds back on the tumor cells to promote further production of PTHrP, which is regulated by the transcription factor Gli2." (PMID 34199096, 2021). "Tumors were significantly affected by gene dosage because reduced tumor burden was observed in Gli2 heterozygous Spop;Sufu double knockout animals." (PMID 34395437, 2021). "Alternative upstream targets include TGF-β which upregulates expression of Gli2 and in turn increases tumor secretion of PTHrP." (PMID 33828987, 2021). "Gli2 repression significantly reduces tumor-induced bone destruction mediated by TGF-β signaling in human breast cancer MDA-MB-231 cells." (PMID 33828987, 2021). "Tumor development in these mice, however, occurs only after conditional removal of primary cilia, as the cilia presence effectively reduced the Gli2 activity." (PMID 34207779, 2021). "Breast tumor cells upregulate GLI2 expression during bone metastasis, stimulating bone resorption, activating TGFβ, and subsequent tumor proliferation." (PMID 33494284, 2021). "The hypoxia condition is reported to promote tumor progression in multiple ways, such as the enhancement of chemoresistance by activating GLI family zinc finger 2 (GLI2) and promotion of tumor metastasis through modulating the macrophage functions." (PMID 35355804, 2021). "Tumor xenografts developed slowly in the sh-Gli2 group compared to the sh-control group, resulting in smaller tumor xenografts." (PMID 35059317, 2021). "Removal of primary cilia abolished tumor development in SmoM2 animals, but accelerated cancerogenesis in mice with conditional expression of active Gli2." (PMID 34207779, 2021). "This was regulated by the hedgehog pathway (Gli2, Bmi1, and Sox 2) to promote tumour initiation and maintenance." (PMID 32316619, 2020). "Despite the limited amount of CSF cfDNA, mutations and most relevant genomic alterations identified in the tumour were also detected in the CSF ctDNA, including MYCN and GLI2 amplification, and partial loss of 17p." (PMID 33110059, 2020). "The in-vivo assays further revealed that circ_0043800 promoted HB tumor growth by up-regulation of Gli2 and STAT3." (PMID 32493490, 2020). "In vitro, Gli2 inhibition led to a reduced proliferation of tumor cells and an increased sensitivity to chemotherapeutic agents." (PMID 32656074, 2020). "GLI2 plays an important role in tumor development and maintenance, and it is found overexpressed in a variety of cancers." (PMID 32544250, 2020). "The ISH evaluated cellular gene expression of Ihh, Smo, Ptch1, Gli1, and Gli2 mRNA both in neoplastic cells and stromal cells comprising the tumor microenvironment." (PMID 32348319, 2020). "We previously reported that the substrate modulus of 2D films regulates tumor cell expression of the transcription factor Gli2 and parathyroid hormone-related protein (PTHrP), both of which have been associated with bone destruction." (PMID 32967150, 2020). "All of the research has demonstrated that GLI2 promoted cell proliferation and exerted a tumour-promoting role in cancer." (PMID 32660514, 2020).
tumor (continued). "In a 143B-induced xenograft model, targeting of Gli2 by genetic invalidation in tumor cells inhibited tumor growth and provided a significant survival benefit." (PMID 32110934, 2020). "In order to evaluate the expression of HH pathway components in canine OSA tumor tissues we performed in situ hybridization for canine Ihh, Smo, Ptch1, Gli1, and Gli2 mRNA on archived, formalin fixed, paraffin-embedded primary canine OSA samples." (PMID 32348319, 2020). "Positive correlation (arbitrary threshold: r > 0.25) between the GLI1 and GLI2 genes was observed in 33/37 tumor types, representing 92.5% (21,825/23,587) of patients." (PMID 32879407, 2020). "Overexpression of GLI1 and GLI2 leads to tumor development in transgenic mice, suggesting that GLI1 or GLI2 contribute to tumorigenesis." (PMID 32784501, 2020). "Some authors have suggested that GANT61 acts selectively by inhibiting GLI1- and GLI2-mediated gene activation in different tumor cells." (PMID 32846867, 2020). "The Xena browser analysis indicated a higher gene expression of GLI1 and GLI2 in primary tumor tissue compared to normal tissue (GLI1; n = 786, p-value = 2.894 × 10−21, GLI1; n = 786, p-value = 6.001 × 10−33)." (PMID 32033067, 2020). "A recent study also reported the decreased expression of miR-141-3p, an miR targeting Gli2 in OS cell lines and tumor samples, suggesting an miR implication in HH-altered pathways in OS." (PMID 32110934, 2020). "Regarding the transcriptional factors Gli1-3, most studies have focused on the role of the transcription factor Gli2 in OS tumor development and progression." (PMID 33228057, 2020). "To further test the role of GLI2 in tumor relapse following KRAS* suppression, we grew iKRAS cell lines (iKRAS1 and iKRAS4) in the presence or absence of Dox for 15–18 days following shRNA mediated knockdown of Gli2." (PMID 31134896, 2019). "Conversely, inhibition of ERAP1 function stabilizes βTrCP, which in turn induces ubiquitylation of Gli factors leading to proteolysis of Gli1 and Gli2 and generation of Gli3R, thereby suppressing tumor cell growth." (PMID 31341163, 2019). "To assess the effect of NT1721 on GLI signaling in vivo we used tumor tissue from individual mice bearing Capan1 tumors for Western blot and qPCR analysis of GLI2 and GLI target genes." (PMID 31661013, 2019). "First, we measured tumor sphere formation efficiency in Colo357-GR cells with GLI2 shRNAs (as Colo357-GR-shGli2) or Colo357-GR cells with a scrambled shRNA (as Colo357-GR-shNC)." (PMID 30382189, 2019). "Of note, treatment with anti-PD-L1 antibodies induced apoptosis of tumor cells derived from GLI2-expressing mouse organoids." (PMID 31878932, 2019). "The results identify GLI2 as tumor-cell intrinsic regulator of PD-L1 expression in gastric cancer, promoting cancer growth via suppression of anti-tumoral responses." (PMID 31878932, 2019). "For example, transforming growth factor-β (TGF-β) has been shown to promote Gli2 expression and is involved in tumor progression and metastasis." (PMID 29423837, 2018). "Gli2 and PD-L1 expression, and proliferation within the patient's native tumor tissue was reflected in the organoid cultures." (PMID 30647844, 2018). "Recently, using a large tumor panel, we identified survivin as another important GLI2 target in more than half of tumor cell types, suggesting a synergy in HH and survivin in forming tumors stemness and maintaining CSC." (PMID 30201866, 2018). "While the Shh pathway is closely associated with CSCs, which represent less than 1% of tumor cells, the majority of NSCLC cells show positive Gli1 and Gli2 expression by immunohistochemistry, suggesting a complex mechanism of Shh pathway activation in NSCLC." (PMID 29581874, 2018).
tumor (continued). "In contrast, knockdown models of Gli2 demonstrated reduced tumor growth in prostatic in vivo models." (PMID 29423837, 2018). "Then, transwell migration, EdU and soft-agar colony formation assays were employed to test effects of ARHGEF16 on glioma cancer cell migration and proliferation, and the effects of GLI2/ARHGEF16 signaling on tumor growth were examined in vivo." (PMID 30305138, 2018). "In western blot analysis, 91.7% (22/24) and 87.5% (21/24) of tumor samples showed higher Gli1 and Gli2 expression than in paired normal tissue, respectively." (PMID 29416661, 2018). "MC1 was used previously to support a role for Hh signalling in tumour-initiating cell regulation and shows elevated GLI2 expression." (PMID 28604738, 2017). "miR-326 is a recognized tumor-suppressing miRNA, in fact among its targets there are Gli2, Smo, Notch1, Notch2 and Nob1." (PMID 28716052, 2017). "Tumor samples with high Gli1 or Gli2 expression showed lower E-Cadherin expression while low Gli expression showed high expression with an epithelial growth pattern." (PMID 27533453, 2016). "In this study, Gli-2 was barely expressed in tumor cells, suggesting that a high level of the ligand SHH can not respond to it in an autocrine fashion." (PMID 27007126, 2016). "Genetic ablation of Krt17 delays tumor development in transgenic mice, suggesting that GLI2-driven KRT17 expression has tumor-promoting activity." (PMID 27512993, 2016). "A multivariate Cox proportional hazards model showed that histologic grade, vascular invasion, Gli2, FoxM1 and KIF20A were significantly associated with tumor recurrence and overall patient survival." (PMID 27036048, 2016). "Many studies on the roles of the HH signaling pathway in NSCLC suggested that GLI1 and GLI2 play central roles in tumor progression, tumor metastasis, and CSC maintenance." (PMID 28105432, 2016). "Parathyroid Hormone-related Protein (PTHrP), has been shown to be essential for mandibular invasion in OSCC animal models, and our previous studies demonstrate that the transcription factor Gli2 increases PTHrP expression in tumor metastasis to bone." (PMID 27738315, 2016). "We further demonstrated the binding of GLI2 to the survivin promoter and the decreased expression of survivin protein and RNA after treatment with GLI2 inhibitor GANT61 in a large panel of tumor cell types." (PMID 26775700, 2016). "Real-time quantitative PCR confirmed reduced Gli1 expression in tumours from wild-type (wt) mice, with a congruent reduction of the Hh targets, Hhip and Gli2." (PMID 27492255, 2016). "Gli-1 and Gli-2 are able to act as tumor suppressors as well as tumor promoters, implying that both proteins are part of a complex network of various signaling cascades." (PMID 27918595, 2016). "If GLI2 is an activator of survivin transcription in cell models, then the positive areas for both proteins should correlate in authentic human tumor sections." (PMID 26775700, 2016). "Silencing of GLI2 inhibited OS tumor formation in nude mice and arsenic trioxide, an inhibitor of GLI2 transcription, also reduced primary OS tumor formation in an OS mouse model." (PMID 25992885, 2015). "Since Hh signaling plays a critical role in mammary stem cell maintenance within the mammary epithelium, it is not surprising that mammary CD44+/CD24−/lowLin− CSCs express increased mRNA transcript levels of PTCH1, GLI1 and GLI2 compared to bulk tumour cells." (PMID 26270676, 2015). "Both are capable of interfering with GLI1 and GLI2-mediated transcription and inhibit tumour cell growth in a GLI-dependent manner (Ref." (PMID 25660620, 2015). "Inoculation of 143B OS cells transfected with GLI2- shRNA resulted in a significant reduction of tumour growth as compared with inoculation of 143B cells transfected with control shRNA." (PMID 25985215, 2015).
tumor (continued). "SMO inhibition alters transcription factors GLI1 and GLI2 to remain inactive, which prevents the expression of tumor mediating genes within the Hh pathway." (PMID 25985215, 2015). "There was also elevated mRNA expression of Shh-signaling pathway genes Gli1, Gli2, Gli3 and Ptch1/2 in both tumor-adjacent skin and BCCs of IR-irradiated mice." (PMID 26413810, 2015). "We report herein that SPOP negatively regulates Hh/Gli2 signaling pathway mediated transcription through interfering Gli2 abundance in gastric cell lines, thus results in decreased tumor cell proliferation, invasion, migration and enhanced cell apoptosis." (PMID 25204354, 2014). "Inhibiting expression of GLI2 in 143B cells transfected with GLI2- shRNA inhibited OS growth and reduced tumor volume 12 weeks after inoculation in nude mice." (PMID 25085524, 2014). "While previous studies have identified GLI1 as the main transcription factor of Hh-GLI signaling pathway in several tumor systems, two independent studies have concluded that GLI2 appears to be of highest relative importance in human OSA." (PMID 24810746, 2014). "Disruption of the primary cilia in Smo-activated tumors inhibits tumor growth, whereas tumor growth is accelerated in Gli2-dependent tumors." (PMID 23880852, 2013). "A high expression level for Gli2 protein was significantly correlated with tumor differentiation, encapsulation, vascular invasion, early recurrence, and intra-hepatic metastasis (P<0.05)." (PMID 23356443, 2013). "The immunohistochemical staining identified the Gli2 location in the cytoplasm and/or nucleus of tumor cells, mainly in the cytoplasm." (PMID 23356443, 2013). "Our lab has developed a novel small molecule, the Gli inhibitor (Gli-I), which specifically inhibits Gli1 and Gli2 transcriptional activity, resulting in dramatic cytotoxicity in tumor cells that are Gli activity dependent." (PMID 23483902, 2013). "The average expression level of gli2 was 2.4 fold as high in tumor tissues as in patient normal pleura (p<0.01), whereas gli1 levels were statistically comparable." (PMID 23483902, 2013). "In a mouse model of BCC, it was suggested that the degree of expression of GLI1 or GLI2 has a critical impact on the development of BCC tumours." (PMID 24163262, 2013). "In vitro, 1D11 was able to block TGFβ induced expression of both Gli2 and PTHrP, which provides a mechanistic explanation of reduced tumor burden in our model." (PMID 22096521, 2011). "Upon reaching the bone microenvironment, tumor cells are exposed to several growth factors including TGFβ which leads to upregulation of Gli2, a hedgehog family transcription factor." (PMID 22096521, 2011). "As a possible mechanism of reduced tumor burden in the bone, 1D11 was able to inhibit TGFβ-mediated upregulation of Gli2 and PTHrP in MDA-MB-231 cells." (PMID 22096521, 2011). "As anticipated, TGFβ-induced expression of Gli2 was decreased when MDA-MB-231 tumor cells were treated with 1D11 (Wilcoxon rank-sum p-value for TGFβ versus TGFβ and 1D11 is 0.005)." (PMID 22096521, 2011). "Together these data strongly support the notion that constitutive Hedgehog signaling is a critical driver in SRBC tumor formation, with overexpression of truncated Gli2 being one mechanism." (PMID 22039523, 2011). "Our observation that the expression of Gli2 by tumor cells is regulated by matrix rigidity is consistent with previous studies suggesting that Hh genes are regulated during development by mechanically transduced signals." (PMID 21085597, 2010). "Gli2, an important transcription factor in the Hedgehog signaling pathway, is not only closely related to the growth of normal cells but is also abnormally activated in various tumor cells." (PMID 41444284, 2025). "Moreover, our analysis of data from clinical GC patients showed a significant correlation between high GLI2 expression and differentiation degree, pathological grade, lymph node metastasis, tumor size, and CDDP resistance." (PMID 40133270, 2025).